JAG1 (jagged canonical Notch ligand 1)
Diseases named in the same sentence as JAG1 in open-access papers (continued):
Sharing a sentence is not in itself a finding about the gene and the disease.
infantile hemangioma (1 paper, 2016). "Interestingly, some of these genes also play roles in cell signaling pathways that have been linked to the pathogenesis of infantile hemangioma; namely, VEGFA in the VEGF/VEGFR pathway, ANGPT2 and ANGPTL1 in the Tie2/Angiopoietin signaling pathway and NOTCH3, NOTCH4 and JAG1 in the Notch pathway." (PMID 26772808, 2016).
Infertility (1 paper, 2019). "A recent study has revealed that NOTCH1 and NOTCH ligands including JAG1 and DLL1 are down-regulated in the endometrium of women with unexplained infertility during the implantation window compared with the fertile subjects." (PMID 31168348, 2019).
inflammatory breast carcinoma (1 paper, 2020). An advanced, invasive breast adenocarcinoma characterized by the presence of distinct changes in the overlying skin. "Furthermore, it was recently shown in vitro that knockdown of Jag1 inhibits the formation of tumor emboli in hybrid E/M inflammatory breast cancer (IBC) – a rare but highly aggressive form of breast cancer that moves largely collectively through clusters – cells SUM149." (PMID 32848867, 2020).
influenza infection (1 paper, 2024). "Moreover, Notch ligands Dll1 and Jag1 were upregulated on migratory DCs from the lung and draining lymph nodes on influenza infection, which in turn primed naïve CD8+ T cells to assemble a specific virus response." (PMID 39209451, 2024).
Kaposi's sarcoma (1 paper, 2022). A malignant neoplasm characterized by a vascular proliferation which usually contains blunt endothelial cells. "In Kaposi sarcoma, JAG1- or delta-like canonical Notch ligand 4 (DLL4)-stimulated signaling results in the suppression of genes associated with the cell cycle in adjacent LECs, indicating a role for Notch signaling in inducing cellular quiescence in LECs." (PMID 36067135, 2022).
latent infection (1 paper, 2009). "Our work suggests that KSHV can establish differential upstream signaling events leading to the expression of DLL4 and JAG1 coincident with lytic and latent infection respectively." (PMID 19816565, 2009).
liver cholestatic diseases (1 paper, 2019). "Genetic tests for liver cholestatic diseases revealed negative results for AGS (JAG1 and NOTCH2)." (PMID 30791938, 2019).
liver failure (1 paper, 2025). A liver disease characterized by the liver losing or has lost all of its function. "Our findings suggest that JAG1+ exosomes derived from regenerating liver tissue may serve as a promising cell-free therapeutic strategy to promote liver regeneration, particularly in clinical contexts such as acute liver injury, post-hepatectomy liver failure, and liver transplantation." (PMID 40796539, 2025).
MELAS (1 paper, 2020). "However, by day 35, mRNA expressions of Notch receptor NOTCH1, NOTCH receptor ligands DLL1 and JAG1 as well as the downstream targets HEY1 and HES5 were significantly higher in day 35 MELAS compared to controls." (PMID 32170107, 2020).
Moyamoya disease (1 paper, 2023). Moyamoya disease (MMD) is a rare intracranial arteriopathy involving progressive stenosis of the cerebral vasculature located at the base of the brain causing transient ischemic attacks or strokes. "Although KVOGM73-1 exhibited no structural cardiac pathology, he had moyamoya disease (MMD), in common with JAG1-mutant patients with AD Alagille syndrome type 175 (OMIM# 118450)." (PMID 37978175, 2023).
MRKH syndrome (1 paper, 2015). "Recently, a valuable gene expression profile of in vitro cultured vaginal tissue from MRKH syndrome patients has identified dysregulation of MUC1, WNT7A, JAG1 and DLL1, emphasizing the critical role of canonical Wnt signaling and the NOTCH pathway." (PMID 26075712, 2015).
muscle atrophy (1 paper, 2019). The loss of muscle tissue due to inactivity or disease. "Here, miR-199b targets JAGGED1 (JAG1) to activate the Notch1 signaling pathway and further promotes the proliferation of porcine muscle satellite cells, suggesting that miR-199b is a potential therapeutic target for muscle atrophy." (PMID 31461973, 2019).
myelodysplastic syndrome (1 paper, 2022). A clonal hematopoietic disorder characterized by dysplasia and ineffective hematopoiesis in one or more of the hematopoietic cell lines. "Intriguingly, transgenic activation of a mutated β-catenin allele was found in murine osteoblasts and it induced myelodysplastic syndrome (MDS) and AML at very early ages via dysregulated Notch ligand JAG1." (PMID 35216168, 2022).
non-alcoholic fatty liver disease (1 paper, 2022). "It has also been demonstrated that the Jag1 activation in hepatocytes reflects Notch pathway activation and is an indicator of non-alcoholic fatty liver disease in human liver biopsy specimens and in a mouse model." (PMID 36355906, 2022).
serous carcinoma (1 paper, 2024). "Those tumors with HRD were all diagnosed as high grade serous carcinoma, specifically harboring fusions involving NRG1 and the JAG1, SPON1, and TNFRSF12A partner genes." (PMID 39575425, 2024).
Strabismus (1 paper, 2020). A misalignment of the eyes so that the visual axes deviate from bifoveal fixation. "JAG1 mutations are reported alongside various clinical features including facial dysmorphology, heart defects, vertebral abnormalities, and ocular dysmorphic features (strabismus, epicanthal folds, and slanted palpebral fissures)." (PMID 32733715, 2020).
urothelial carcinoma (1 paper, 2014). A malignant neoplasm derived from the transitional epithelium of the urinary tract (urinary bladder, ureter, urethra, or renal pelvis). "Expression of NOTCH1, DLL1 and JAG1 was further analysed by immunohistochemistry in a set of paraffin-embedded tissues covering urothelial carcinomas of all stages and grades." (PMID 25167871, 2014).
vascular dementia (1 paper, 2021). A degenerative vascular disorder affecting the brain. "The H2S generating molecule sodium hydrosulfide (NaHS) has been shown to activate Notch pathway by increasing Jag1 and Hes1 in the hippocampus in a vascular dementia rat model." (PMID 34336718, 2021).
villous adenoma (1 paper, 2018). An epithelial neoplasm morphologically characterized by the presence of a villous architectural pattern. "In addition, ApcMin/+ mice carrying the different Jag1 genotypes showed a comparable distribution of dysplastic crypts, tubular and villous adenomas, indicating that Jag1 requirement is not restricted to any particular tumor subtype." (PMID 30065304, 2018).
tumor (369 papers, 2006 to 2026). "In the context of CRC, deletion of a single JAG1 allele in an APC mutant background significantly reduces tumor burden, which is associated with decreased levels of active Notch1." (PMID 41294868, 2025). "JAG1, a cell surface ligand of the Notch signaling pathway, is highly expressed in numerous cancers that are closely associated with tumor biology and is inversely associated with the prognosis of these cancers." (PMID 37965333, 2023). "Immunostaining of HCC tissues from Jag1-MxKO mice confirmed a complete loss of Jag1 expression, but Hes1 expression remained unchanged, especially in the peripheral regions of the tumor." (PMID 35064244, 2022). "In contrast, Jag1 deletion induces the ectopic expression of Dll4 in hepatocytes along with the loss of Notch2 signaling, leading to the tumor progression." (PMID 35064244, 2022). "The high expressions of endothelial cells’ Jag1 increase tumor in the blood vessel system, but the loss of Jag1 meaning in endothelial cells reduces vasculature and growth of tumors." (PMID 35406423, 2022). "It is suspected that Jag1 serves as a communication factor between cancer cells and tumor-associated ECs (TECs) to activate Notch signaling and induce angiogenesis by increasing cell proliferation and stabilizing vessels." (PMID 33681228, 2021). "Collectively, Jag1 can act as a tumor suppressor in the pancreas by delaying precursor lesions, whereas loss of Jag1 promoted a phenotypic switch from malignant carcinoma to benign cystic lesions." (PMID 33268505, 2021). "N110–24 demonstrated potent antitumor effects in various murine tumor models by reducing angiogenic sprouting and disruption of tumor endothelium, both of which are phenotypes associated with JAG1-driven Notch signaling." (PMID 32922403, 2020). "This was associated with low tumor infiltration of CD11c+Gr1+ cells, thereby providing further evidence of JAG1 as a factor mediating immunosuppressive tolerogenic responses." (PMID 32922403, 2020). "Meanwhile, multiple associations between Jag1/Notch signaling and other oncogenic factors in regulating tumor microenvironment were reported, including interleukins, TGF-β, and the Hippo, Wnt/β-catenin, and NF-κB signaling pathways." (PMID 33329315, 2020). "The further decrease in the expression of CD24 and up-regulation of JAG1 following AnxA6 down-regulation suggest that reduced expression or loss of AnxA6 is associated with poorly differentiated, highly proliferative tumor cells." (PMID 30719209, 2019). "JAG1 has been implicated in different aspects of cancer biology including tumor angiogenesis, neoplastic cell growth and the metastatic process." (PMID 31354524, 2019). "It induces proliferation and migration processes through Notch-1, yes-associated protein 1 (YAP), Jagged-1 (Jag-1) and hairy and enhancer of split-1 (Hes-1) and the down-regulation of its expression reduces tumor growth in vivo." (PMID 30583549, 2018). "Since JAG1 overexpression has been implicated in metastasis, we then investigated the role of JAG1 in ATL tumor cell migration by wound assays in vitro." (PMID 30231940, 2018). "Tumor vaginal involvement (93.8%; p = 0.004), lymph nodes metastasis (90.8%; p = 0.05) and Figo stage (93.8%; p = 0.004) were found to be associated with JAG1 expression." (PMID 29921897, 2018). "Immunohistochemical expression of JAG1, with respect to clinicopathological parameters, showed its association with the tumor vaginal involvement, Figo stage and lymph node metastasis, highlighting its clinical utility in ISCC." (PMID 29921897, 2018). "JAG1 overexpression showed an association with lymph nodes metastasis (90.8%; p = 0.01), vaginal involvement of tumor (92.3%; p = 0.003), as well as with Figo stage (92.3%; p = 0.003) respectively." (PMID 29921897, 2018). "The average final tumor volume in the endothelial Jag1 loss-of-function mutants was only 300 mm3, less than half of that of the respective controls (650 mm3)." (PMID 26213336, 2015).
tumor (continued). "Over-expression of endothelial Jag1 culminated in increased perfusion and decreased extravasation, while endothelial loss-of-function caused the tumor vasculature to be less perfused and leakier." (PMID 26213336, 2015). "After verifying that modulation of endothelial Jag1 caused such significant alterations in the growth of LLC subcutaneous tumor transplants, we investigated its effect in an autochthonous tumor model." (PMID 26213336, 2015). "In contrast, loss of endothelial Jag1 led to significantly delayed tumor growth, from day eleven after injection." (PMID 26213336, 2015). "Conversely, endothelial Jag1 loss-of-function led to a sparse, immature, and poorly functional neo-vessel network that substantially inhibits tumor growth." (PMID 26213336, 2015). "The role of endothelial Jagged1 in tumor growth and neo-angiogenesis was investigated with endothelial-specific Jag1 gain- and loss-of-function mouse mutants (eJag1OE and eJag1cKO)." (PMID 26213336, 2015). "In fact, JAG1-stimulated Notch activation is directly implicated in tumor growth through maintaining cancer stem cell populations, promoting cell survival, inhibiting apoptosis, and driving cell proliferation and metastasis." (PMID 25309874, 2014). "Our results show an association between BMI, tumor grade, and the induction of JAG1 in TNBC cells." (PMID 39408921, 2024). "However, the expression of Notch and Jag1 was associated with a better outcome only in those patients with a poor tumor vascularization." (PMID 36925919, 2023). "The mechanism of Notch signaling involved in tumor vascular remodeling is that the overexpression of Jag1 in endothelial cells (ECs) leads to the increase of tumor vascular system, while the loss of Jag1 function in ECs leads to the decrease of vascular system and tumor growth." (PMID 35965504, 2022). "JAG1 is a major component of the Notch pathway and has been linked to normal biological processes, including tissue homeostasis, adult stem cell control, and oncogenic functions, including carcinogenesis, vascularization, and tumor growth." (PMID 36476410, 2022). "In contrast, pharmacological treatment with monomeric soluble JAG1 resulted in remarkable inhibition of tumor growth that was associated with the down-regulation of Treg cell differentiation, significantly decreased tumor infiltration with CD11c+Gr1+ cells, and enhanced IFN-γ production." (PMID 30940183, 2019). "Similarly, JAG1 was associated with tumor vaginal involvement (93.8%; p = 0.001), lymph nodes metastasis (92.3%; p = 0.02) as well as with Figo stage (93.8%; p = 0.004) respectively." (PMID 29921897, 2018). "Importantly, lower tumor expression of MFNG significantly associated with poor CRC prognosis specifically in the group of JAG1-high tumors." (PMID 30065304, 2018). "Both Delta-like 4 (DLL4) and Jagged1 (JAG1) ligands are implicated in tumour angiogenesis." (PMID 28445154, 2017). "Delta-like 4 (DLL4) and Jagged1 (JAG1) are two key Notch ligands implicated in tumour angiogenesis." (PMID 28445154, 2017). "Here we demonstrate for the first time the effect of directly modulating endothelial Jagged1 in tumor angiogenesis and growth, confirming that loss of endothelial Jag1 has a strong anti-angiogenic effect that inhibits tumor growth and the acquisition of an invasive phenotype." (PMID 26213336, 2015). "JAG1 overexpression in tumors contributes to tumor growth, metastasis, recurrence, and drug resistance by promoting cancer cell survival, proliferation, metastasis, cancer stem cell expansion, and tumor-associated angiogenesis, and by inhibiting tumor-specific immunity." (PMID 36979394, 2023). "Previous reports suggest that Jag1 is associated with the acquisition of immune regulatory functions in CD4+ T cells and is also linked to immune evasion within the tumor microenvironment." (PMID 40702356, 2025).
tumor (continued). "To investigate the role of CD46-JAG1 signaling pathway in NPC, we performed in vitro functional experiments to confirm the effect of JAG1 on NPC tumor cells." (PMID 39744570, 2025). "CCK-8 assay indicated that tumor cell viability was significantly decreased in the JAG1 knockdown group compared with the control group." (PMID 39744570, 2025). "Exosomes from a stiff matrix exhibited elevated JAG1 expression and enhanced tumor proliferation through Notch activation." (PMID 40796539, 2025). "Consistent with the results of previous studies, knockdown of JAG1 also inhibited the migration and invasion of both tumor cells, and the results were statistically significant." (PMID 39744570, 2025). "Exosomes from a stiff matrix show increased JAG1 protein expression, promoting tumor proliferation and invasion via Notch pathway activation." (PMID 40796539, 2025). "Next, we confirmed the effect of JAG1 on the migration and invasion ability of tumor cells by scratch assay and Transwell assay." (PMID 39744570, 2025). "Our data shows that the NOTCH3 receptor gene is highly expressed in α‐SMA+ stroma compartments across all three tumor grades, and its ligand gene JAG1 is upregulated in tumor compartments of G1 tumors." (PMID 39245631, 2025). "Of note, primary PCa tumours showed high JAG1, GP2, GLO1, NPR3, VGLL3, CHRNA2 and SEMA3F mRNA levels in primary PCa tissue samples." (PMID 40219635, 2025). "According to the same study results, PRAT area expansion has been associated with VEGFA, JAG1, and TGF-β1 pro-angiogenesis gene expression increases, suggesting a possible interplay between PRAT-derived leptin activity and tumor angiogenesis." (PMID 40227577, 2025). "Exosomes from a stiff matrix show elevated JAG1 expression and enhanced tumor proliferation via Notch activation." (PMID 40796539, 2025). "We therefore performed in vitro functional experiments to confirm the effects of JAG1 on tumor cells." (PMID 39744570, 2025). "Proteins that increase JAG1 in the tumor microenvironment are proinflammatory cytokines, including IL-6." (PMID 39408921, 2024). "Treatment with an anti-JAG1 antibody can inhibit the JAG1/Notch signaling pathway in both tumor cells and the microenvironment, thereby delaying tumor recurrence." (PMID 38672455, 2024). "The JAG1–Notch pathway drives tumor progression through mechanisms like cyclin D1 regulation, the induction of epithelial–mesenchymal transition (EMT), and the enhancement of invasive ability." (PMID 38474093, 2024). "Functionally, JAG1 activates the Notch pathway in bone cells, fostering tumor growth by inducing IL-6 release from osteoblasts and promoting osteoclast differentiation." (PMID 38474093, 2024). "Jag1 participates in different mechanisms involved in tumorigenesis, including tumor growth, maintenance of CSCs, angiogenesis, invasion, metastasis, and immune evasion." (PMID 39735530, 2024). "The role of JAG1 in the tumor microenvironment agrees with the BMI effect we identified in our study that shows that a BMI increase is associated with increased expression of JAG1, migration, and invasiveness in MDA-MB-231 cells." (PMID 39408921, 2024). "CTX014, an inhibitor of Jag-1, can limit tumor growth and recruitment of MDSCs by blocking Arginase1 and iNOS." (PMID 39735530, 2024). "The experimental results demonstrate that silencing JAG1 yielded a significant decrease in tumor cell proliferation in LGG cell lines." (PMID 38022677, 2023). "LN229-derived tumor margins showed a higher frequency of cell population expressing JAG1 than those of U87MG-derived tumors." (PMID 38092725, 2023). "JAG1 can not only participate in the growth, proliferation, and migration of tumor cells but can also promote the formation of treatment tolerance." (PMID 38203424, 2023). "It was reported that JAG1 expression in the cytoplasm is correlated with the expression of NOTCH3 in tumor cells, suggesting an interaction between these two proteins." (PMID 37860822, 2023).